IGFBP3 (insulin like growth factor binding protein 3)
Description:
Multifunctional protein that plays a critical role in regulating the availability of IGFs such as IGF1 and IGF2 to their receptors and thereby regulates IGF-mediated cellular processes including proliferation, differentiation, and apoptosis in a cell-type specific manner. Also exhibits IGF-independent antiproliferative and apoptotic effects mediated by its receptor TMEM219/IGFBP-3R. Inhibits the positive effect of humanin on insulin sensitivity. Promotes testicular germ cell apoptosis. Acts via LRP-1/alpha2M receptor, also known as TGF-beta type V receptor, to mediate cell growth inhibition independent of IGF1. Mechanistically, induces serine-specific dephosphorylation of IRS1 or IRS2 upon ligation to its receptor, leading to the inhibitory cascade. In the nucleus, interacts with transcription factors such as retinoid X receptor-alpha/RXRA to regulate transcriptional signaling and apoptosis.
Synonyms: IBP-3; IGFBP-3; IBP3; BP-53
Tractability: Small molecule: it belongs to a druggable protein family. Antibody: UniProt places it where antibodies can reach, with high confidence; its Gene Ontology location is reachable by antibodies, with high confidence; UniProt predicts a signal peptide or a membrane-spanning region. PROTAC: its protein half-life has been measured; a small molecule that binds it is known.
Target class: Secreted protein
Gene: Protein-coding gene on chromosome 7 (45,912,245 to 45,921,874, reverse strand). Ensembl gene ENSG00000146674.
Subcellular location: Secreted; Nucleus
Subcellular location (Human Protein Atlas): Vesicles; Predicted to be secreted
Pathways (Reactome):
Metabolism of proteins: Post-translational protein phosphorylation; Regulation of Insulin-like Growth Factor (IGF) transport and uptake by Insulin-like Growth Factor Binding Proteins (IGFBPs)
Gene Ontology:
Molecular function: insulin-like growth factor I binding; protein binding; protein tyrosine phosphatase activator activity; fibronectin binding; insulin-like growth factor binding; insulin-like growth factor II binding; metal ion binding
Biological process: negative regulation of cell population proliferation; negative regulation of protein phosphorylation; negative regulation of smooth muscle cell migration; negative regulation of smooth muscle cell proliferation; positive regulation of apoptotic process; positive regulation of myoblast differentiation; protein phosphorylation; negative regulation of signal transduction; regulation of insulin-like growth factor receptor signaling pathway; osteoblast differentiation
Cellular component: extracellular region; insulin-like growth factor ternary complex; nucleus; endoplasmic reticulum lumen; insulin-like growth factor binding protein complex; non-collagenous component of interstitial matrix
Genetic constraint (gnomAD): Loss-of-function variants: 9 observed, 18.09 expected, observed/expected ratio (o/e) 0.5, 90% interval 0.3 to 0.87. The synonymous counts are far from expectation, so gnomAD's model fits this gene poorly and the ratio says little. Missense variants: 381 observed, 334.38 expected, observed/expected ratio (o/e) 1.14, 90% interval 1.05 to 1.24. Synonymous variants: 185 observed, 137.85 expected, observed/expected ratio (o/e) 1.34, 90% interval 1.19 to 1.52.
Homologues: Orthologues: chimpanzee IGFBP3 (100% identical), macaque IGFBP3 (99% identical), pig IGFBP3 (84% identical), guinea pig IGFBP3 (83% identical), rat Igfbp3 (82% identical), mouse Igfbp3 (82% identical), dog IGFBP3 (81% identical), zebrafish igfbp3 (50% identical). Paralogues in human: IGFBP5 (38% identical), IGFBP2 (31% identical), IGFBP6 (28% identical), IGFBP4 (27% identical), IGFBP1 (25% identical).
Diseases named in the same sentence as IGFBP3 in open-access papers:
IGFBP3 is named in the same sentence as 404 diseases in open-access papers, as found by Europe PMC text mining. Sharing a sentence is not in itself a finding about the gene and the disease. The quoted sentences say what the papers report.
breast carcinoma (192 papers, 1996 to 2026). "In contrast, a case-control study of 2,503 Chinese women in Shanghai found that individuals carrying the C allele of the IGFBP-3 A-202C polymorphism had a 1.6-fold increased risk of developing breast cancer." (PMID 40493660, 2025). "Our study further demonstrates a similar association between the IGFBP-3 SNP rs2854744 and breast cancer risk in both pre-and post-menopausal women." (PMID 40493660, 2025). "This study found a significant association between the IGFBP-3 A-202C polymorphism and breast cancer risk among Palestinian women in the Gaza Strip." (PMID 40493660, 2025). "The study’s focus on Palestinian women addresses a critical gap in breast cancer research, as data on the IGFBP-3 A-202C polymorphism in Middle Eastern populations are scarce." (PMID 40493660, 2025). "The study’s findings on the IGFBP-3 A-202C polymorphism in Palestinian women in the Gaza Strip highlight potential population-specific genetic, and biochemical influences on breast cancer risk." (PMID 40493660, 2025). "Further analysis showed that women with the CC genotype of IGFBP-3 A-202C had a 16-fold higher risk of breast cancer compared to those with other genotypes (OR=16.237; 95%CI 7.904, 33.356, p ≤ 0.001)." (PMID 40493660, 2025). "The analysis of the IGFBP-3 A-202C polymorphism’s gene distribution in 112 newly diagnosed women with breast cancer and 222 healthy controls was conducted." (PMID 40493660, 2025). "The CC genotype of IGFBP-3 A-202C was observed in 70.5% of cases and 20.7% of controls, conferring a 16-fold increased breast cancer risk (OR=16.237; 95%CI 7.904, 33.356, p ≤ 0.001)." (PMID 40493660, 2025). "Further, higher IGFBP-3 in breast tumors is associated with worsened relapse-free breast cancer patient survival." (PMID 39619437, 2024). "Taken together, these data identify a novel mechanism of IGFBP-3 regulation in breast cancer cells and provide evidence for an association between IGFBP-3 and response to antiestrogen therapies." (PMID 39619437, 2024). "Through epidemiologic studies, high levels of IGFBP3 are associated with decreased risk of several common cancers, including PCa, breast cancer, colorectal cancer and lung cancer." (PMID 37624511, 2023). "The association between IGFBP-3 and breast cancer risk is reportedly due to its interaction with IGF-1, and this interaction can be eliminated by the adjustment of IGF-1, suggesting that IGF-1 itself is an inducing factor of breast cancer." (PMID 36755926, 2023). "Based on these studies, increased levels of circulating IGF-1 and IGFBP3 are considered risk factors for breast cancer." (PMID 37108716, 2023). "According to a systematic evaluation, higher levels of IGF-1, IGFBP-3 and leptin and lower levels of adiponectin among obesity-associated protein biomarkers are correlated with an increased breast cancer risk." (PMID 36755926, 2023). "Our findings showed that variants of energy homeostasis genes modified the association between the IGF-1 or IGFBP-3 serum concentration and breast cancer risk in premenopausal women." (PMID 35115550, 2022). "The aim of this study was to assess the modifying effect of the genetic variation in some energy homeostasis genes on the association of serum concentrations of IGF-1 and IGFBP-3 with breast cancer risk." (PMID 35115550, 2022). "Circulating levels of IGF-1 and its binding protein, IGFBP3, have been linked to breast cell proliferation and breast cancer risk." (PMID 36672557, 2022). "Studies have shown that elevated circulating levels of IGF-1 and reduced levels of IGFBP-3 are associated with an increased risk of premenopausal breast cancer." (PMID 36482346, 2022). "The present study demonstrates that preoperative levels of IGF-I or IGFBP-3 (tertiles) are positively associated with risk of breast cancer recurrence, which is in contrast to a recent study of Danish postmenopausal patients." (PMID 33767994, 2021).
breast carcinoma (continued). "The relation of circulating IGF-I and IGFBP-3 concentrations with risk of breast cancer recurrence has been less documented." (PMID 33767994, 2021). "This review highlights the different mechanisms by which cytokines, IGF-1, and IGFBP-3 levels increase the risk of developing breast cancer." (PMID 32528752, 2020). "Results using the three approaches cumulatively suggests that loss of GRP78 promotes the tumorigenic actions of IGFBP-3 and predicts a poor prognosis in patients with breast cancer." (PMID 33352865, 2020). "In breast cancer and glioblastoma, high expression levels of IGFBP-3 in cancer tissues are associated with decreased survival rates." (PMID 32093285, 2020). "Confirming our previous observations, the survival benefits of IGFBP-3 expression in breast cancer were consistently associated with high IGFBP-3 expression, while the effect of TMEM219 was more diverse and subgroup-specific." (PMID 32443727, 2020). "This IGF-1/IGFBP-3 ratio is essential in determining breast cancer risk coupled with other factors, such as age, hormonal use, and family history." (PMID 32528752, 2020). "Two SNPs within two genes (rs2229765-AA [IGF1R] and rs2854744-CC [IGFBP3]) showed significant protection associations (rs2229765-AA: OR 0.82, P=.001; rs2854744-CC: OR 0.88, P=.03) for breast cancer." (PMID 32554381, 2020). "Together, our data suggest that loss of GRP78 reduces IGFBP-3 entry into cells switching its actions to promote tumorigenesis and predicts a poor prognosis in breast cancer patients." (PMID 33352865, 2020). "Insulin-like growth factor (IGF-1) and its primary binding protein (IGFBP-3) are known risk factors for breast cancer due to their ability to stimulate mitosis and suppress programmed cell death." (PMID 33092613, 2020). "Insulin-like growth factor 1 (IGF-1) and binding protein 3 (IGFBP-3) are associated with breast cancer in women at average risk of cancer." (PMID 33092613, 2020). "Estrogen enhances the effect of IGF-1 levels on breast cancer cell growth and modulates the effect of IGFBP-3 levels on premenopausal breast cancer risk." (PMID 32528752, 2020). "In conclusion, circulating IGF-1 expression in HER2-positive breast cancer patients was associated with menopausal status and IGFBP-3 level." (PMID 32391265, 2020). "Together, our clinical and experimental results suggest that loss of GRP78 reduces IGFBP-3 entry into cells switching its actions to promote tumorigenesis and predicts a poor prognosis in breast cancer patients." (PMID 33352865, 2020). "Several studies have shown that high tumor levels of IGFBP-3 are associated with more aggressive breast cancer and decreased overall survival." (PMID 31693710, 2019). "Prior studies have found positive associations between circulating IGF-I and the IGF-I:IGFBP-3 ratio and breast cancer risk." (PMID 31337427, 2019). "For example, SPP1 (also known as osteopontin) is known to promote glioma progression by regulating GBM-associated macrophage infiltration, while IGFBP3 impairs T cell accumulation in breast cancer." (PMID 31477638, 2019). "Studies have shown that high levels of IGFBP-3 predicted distant recurrence of breast cancer in postmenopausal women and high levels of IGFBP-3 have been found in tissue of breast tumors associated with poor prognosis." (PMID 28702218, 2018). "While higher levels of IGF-I and IGF-I/IGFBP-3 ratio are associated with an increased risk of death from breast cancer and CRC, alternative findings have been observed in other studies." (PMID 28143425, 2017). "High levels of MTA1 and high levels of IGFBP3 associates with a poor relapse-free and metastasis-free survival of breast cancer patients." (PMID 28393842, 2017).
breast carcinoma (continued). "In breast cancer tissue, IGFBP-3 is predominantly associated with ER-negative tumors, with much lower expression in ER-positive breast cancer." (PMID 28778177, 2017). "To assess the clinical significance of MTA1/DNMT3a/IGFBP3 axis in breast cancer, we performed a two-way correlation involving low levels of DNMT3a and high levels of IGFBP3 associated with a poor distant metastasis-free survival." (PMID 28393842, 2017). "ER-negative breast tumors also typically have higher expression of IGFBP-3 mRNA and protein than ER-positive tumors, and in women with breast cancer of the basal-like subtype, high IGFBP-3 is significantly associated with poorer recurrence-free survival." (PMID 28778177, 2017). "Increased levels of circulating IGFBP-3 have been associated with both increased BMI and increased risk of premenopausal breast cancer." (PMID 27448965, 2016). "This study has revealed that IGFBP-3 is integrally involved in the mechanism underlying the enhanced response of mammary tumors to an obese environment." (PMID 27448965, 2016). "Higher bioactive levels of IGF1, most accurately represented by the molecular ratio of circulating IGF1 to IGFBP3, have been shown to be associated with breast cancer mortality." (PMID 25619494, 2015). "Although some epidemiologic studies support an association between IGFBP-3 and risk of breast cancer among younger women, results to date have been inconsistent." (PMID 26251693, 2015). "The ratio between IGF-1 and serum IGFBP-3 was associated with increased mortality, suggesting a potential prognostic biomarker value of this ratio in breast cancer." (PMID 26217584, 2015). "In the context of breast cancer, IGFBP-3 and IGFBP-5, secreted by carcinoma-associated fibroblasts (CAFs), inhibit detachment-induced cell death, known as anoikis, via regulation of ERK-MAPK activation." (PMID 26217584, 2015). "Some studies have reported that high serum levels of IGFBP-3 are associated with increased risk of breast cancer in pre- and or post-menopausal women; however, several studies were unable to confirm this finding." (PMID 26217584, 2015). "Statistically significant, positive associations were observed between IGF-I and IGFBP-3 and breast cancer risk among younger women." (PMID 26251693, 2015). "In breast cancer, it was shown that 1, 25-D3 causes cyclical IGFBP-3 mRNA accumulation with a periodicity of 60 min." (PMID 23690781, 2013). "Our study demonstrates that long-range interactions of cancer-related loci, including EGFR and IGFBP3, are altered in breast cancer cells, and these alterations are frequently associated with epigenetic changes." (PMID 24019942, 2013). "Insulin-like growth factor binding protein 3 (IGFBP3) has been implicated in breast cancer pathogenesis." (PMID 24019942, 2013). "Our laboratory and others have demonstrated a significant association of high IGF-I circulatory levels, low IGFBP-3 levels, and a correlation with breast cancer risk and outcome, notably among African-American and Hispanic/Latina women." (PMID 24167614, 2013). "The expression of IGFBP3 is upregulated in oral SCC tumors and cell lines and in breast cancer, in which the expression of IGFBP3 is associated with poor outcome." (PMID 22427941, 2012). "By contrast, adjustment of the association between IGFBP3 and breast-cancer risk for IGF1 reduced the OR for linear trend from 1·12 (95% CI 1·00–1·26) to 0·99 (0·87–1·14)." (PMID 20472501, 2010). "In this study we undertook a collaborative analysis of data from 17 studies to investigate the associations of IGF1 and IGFBP3 with breast-cancer risk." (PMID 20472501, 2010). "In postmenopausal women the findings are less clear and positive association of either IGF1, IGFBP3 or both with breast cancer has been reported while other studies are negative." (PMID 20302654, 2010).
breast carcinoma (continued). "The polymorphism rs6220 has also been correlated with elevated IGF1 levels whereas homozygosity G/G of rs2162679, has been associated with reduced breast cancer risk as well as reduced levels of IGFBP3." (PMID 20302654, 2010). "IGF receptor I expression in primary breast cancer has also been suggested as an independent favorable prognostic factor, while IGF binding protein-3 (IGFBP-3) expression is associated with a poor outcome of breast cancer." (PMID 24281091, 2010). "Variation in IGFBP3 concentrations by breast-cancer risk factors was less pronounced than that for IGF1 (webappendix p 2)." (PMID 20472501, 2010). "IGFBP3 was positively associated with breast-cancer risk, but this association was weak, and was eliminated by adjustment for IGF1, suggesting that the association of IGFBP3 with risk is due to its positive correlation with IGF1." (PMID 20472501, 2010). "Whilst an attractive model, other studies report that IGFBP3 can potentiate EGF-stimulated proliferation in MCF10A cells and that IGFBP3 expression is associated with growth stimulation of T47D human breast cancer cells." (PMID 20840765, 2010). "When we compared the highest to the lowest levels of IGFBP-3, the people in the highest strata had a 0.68(95%CI: 0.48~0.88) times higher risk of developing breast cancer." (PMID 19549343, 2009). "Other studies have primarily examined individual variants in IGF1, IGFBP1, or IGFBP3 in relation to breast cancer with mixed results." (PMID 18596909, 2008). "Some studies report that these or other IGF polymorphisms modestly affect circulating levels of IGF-I and IGFBP-3, but there is limited support for a direct effect on breast cancer risk." (PMID 18596909, 2008). "We comprehensively examined the association between common genetic variation in the IGF1, IGFBP1, and IGFBP3 genes in relation to circulating IGF-I and IGFBP-3 levels and breast cancer risk within the NCI Breast and Prostate Cancer Cohort Consortium (BPC3)." (PMID 18596909, 2008). "Previous epidemiologic studies have suggested that high circulating levels of IGF-I and low levels of IGFBP-3 are associated with increased risk of premenopausal breast cancer." (PMID 18596909, 2008). "Our study is by far the largest to examine genetic variation in the IGF1, IGFBP1, and IGFBP3 genes in relation to both circulating IGF-I and IGFBP-3 levels and breast cancer risk." (PMID 18596909, 2008). "As to IGFBP-3, high concentrations were only correlated to increased risk of premenopausal breast cancer." (PMID 18781172, 2008). "No consistent interactions were observed among variants in the IGF1, IGFBP1, and IGFBP3 genes with any of the following: first-degree family history of breast cancer, ever oral contraceptive use, use of postmenopausal hormones, and BMI (<25, 25-<30, 30+)." (PMID 18596909, 2008). "Our data show that associations of some breast cancer risk factors with intact levels of IGFBP-3 are different from those with total (intact and fragmented) IGFBP-3 levels." (PMID 18471292, 2008). "Here, we examine the association of breast cancer risk factors with intact and total IGFBP-3 levels." (PMID 18471292, 2008). "Numerous recent epidemiologic studies have begun to examine variation in the genes encoding IGF1, IGFBP1, and IGFBP3 in relation to breast cancer risk." (PMID 18596909, 2008). "This is the first epidemiologic study to examine the association of intact and total IGFBP-3 measurements with a large set of breast cancer risk factors, including mammographic breast density." (PMID 18471292, 2008). "The associations of several breast cancer risk factors with IGFBP-3 levels vary in strength and even direction depending on the molecular form of IGFBP-3." (PMID 18471292, 2008). "Levels of insulin-like growth factor (IGF)-I and its main binding protein (IGFBP-3) have been associated with breast cancer risk among premenopausal women." (PMID 18471292, 2008).